Y_RNA (Y RNA )
Gene: Miscellaneous RNA gene on chromosome 7 (99,936,610 to 99,936,711, forward strand). Ensembl gene ENSG00000199711.
Homologues: Orthologues: chimpanzee Y_RNA (99% identical), macaque Y_RNA (93% identical). Paralogues in human: Y_RNA (87% identical), Y_RNA (86% identical), RNY3 (85% identical), RNY3P9 (85% identical), Y_RNA (85% identical), Y_RNA (84% identical), RNY3P1 (83% identical), RNY3P16 (83% identical), Y_RNA (83% identical), Y_RNA (82% identical), RNY3P14 (81% identical), Y_RNA (81% identical), and 94 more.